MMP9 (matrix metallopeptidase 9)
Diseases named in the same sentence as MMP9 in open-access papers (continued):
Sharing a sentence is not in itself a finding about the gene and the disease.
central serous retinopathy (1 paper, 2012). Central serous retinopathy, also known as central serous chorioretinopathy, is an eye disease that causes visual impairment, usually in one eye. "Future studies of other retinal conditions such as central serous retinopathy will determine if there is also a correlation between MMP-9 and SRF." (PMID 22773904, 2012).
Cerebral atrophy (1 paper, 2025). Atrophy (wasting, decrease in size of cells or tissue) affecting the cerebrum. "The plasma inflammatory markers centered on neutrophils—MMP-9 and IL-18—interact with various risk factors (age, gender, DMTS, DWMH, cerebral atrophy) and contribute to the development of PSCI." (PMID 40821836, 2025).
cerebral toxoplasmosis (1 paper, 2020). Infections of the brain caused by the protozoan toxoplasma gondii that primarily arise in individuals with immunologic deficiency syndromes (see also aids-related opportunistic infections). "During cerebral toxoplasmosis, MMP-9 plays a role in the degradation of the extracellular matrix components and in the extravasation of leukocytes in the inflammation sites." (PMID 32460746, 2020).
childhood cancer (1 paper, 2020). "The approach here finds that blockade of MAPK7/MMP9 signalling may overcome current hurdles for targeting pathways that ultimately lead to metastatic lung nodule formation in a childhood cancer." (PMID 32655131, 2020).
Chlamydia infection (1 paper, 2025). "During Chlamydia infection, neutrophils are the primary producer of MMP-9 (also known as gelatinase B)." (PMID 40005489, 2025). "Increased levels of MMP-9 may promote epithelial necrosis and sloughing in the FRT during Chlamydia infection, allowing dissemination of infection as infected epithelial cells are released." (PMID 40005489, 2025).
choledocholithiasis (1 paper, 2022). Presence or formation of gallstones in the common bile duct. "A study found that TIMP-1 and MMP-9 are differentially expressed in the bile of patients with CCA and choledocholithiasis, but they have low diagnostic specificity and accuracy and, thus, are possible but less likely to serve as a diagnostic marker of CCA." (PMID 36010914, 2022).
Cholestatic liver disease (1 paper, 2026). "Animal experiments demonstrated that melatonin alleviated inflammation and fibrosis in cholestatic liver disease, downregulated MMP9 expression, and upregulated the expression of EGFR, AKT, and phosphorylated AKT." (PMID 41758906, 2026).
chorioretinal disease (1 paper, 2020). "Our study design does not allow conclusions on whether or not MMP-9 vs. TIMP-1 imbalances play a role in local chorioretinal disease development—but only that a general imbalance in extracellular matrix homeostasis is not present in Caucasians with PCV." (PMID 32429088, 2020).
choroidal melanoma (1 paper, 2015). Malignant tumor of melanocytes of the choroid. "Others have reported that inhibition of EphA2 expression may down-regulate expression of MMP-9 in a murine choroidal melanoma model, and PI3K may be the mediator in this regulatory pathway." (PMID 25788424, 2015).
chronic allograft nephropathy (1 paper, 2013). "In the present study, we investigated the expression of MMP-9 and its role, with F334 to LEW transplant rat model, in the early stage (12 weeks post-transplantation) of chronic allograft nephropathy which represents the most common cause of late graft failure." (PMID 23351884, 2013).
chronic cervicitis (1 paper, 2024). Chronic inflammation of the cervix. "We used a set of patient-derived precancerous (n = 32) and noncancerous (chronic cervicitis; n = 10) tissue samples to investigate the gene expression of several OIS (LMNB1, CDKN2A, CDKN2B, and CDKN1A), and SASP (IL1A, CCL2, TGFB1, CXCL8, and MMP9) biomarkers using qRT-PCR." (PMID 39727946, 2024).
chronic gastritis (1 paper, 2023). Inflammation of the stomach that is chronic in nature. "Positive correlation between MMP-9 and the activity of inflammation was also observed in children with H. pylori-related chronic gastritis." (PMID 37958643, 2023).
chronic inflammatory demyelinating polyneuropathy (1 paper, 2012). "Elevated MMP-2 and MMP-9 immunoreactivity was found in nerve tissue in chronic inflammatory demyelinating polyneuropathy (CIDP) and nonsystemic vasculitic neuropathy (NSVN), compared to noninflammatory neuropathies (NINs)." (PMID 22970361, 2012).
chronic otitis media (1 paper, 2025). Chronic form of otitis media (disease). "Our study provides direct evidence that both MMP-2 and MMP-9 are produced locally during the process of tympanosclerosis and/or chronic otitis media." (PMID 40468054, 2025). "Our study provides direct evidence that both MMP-2 and MMP-9 are produced locally during tympanosclerosis and/or chronic otitis media." (PMID 40468054, 2025).
chronic thromboembolic pulmonary hypertension (1 paper, 2023). Chronic thromboembolic pulmonary hypertension (CTEPH) is characterized by the persistence of thromboemboli in the form of organized tissue obstructing the pulmonary arteries. "Certain studies have proven that patients with CTEPH (chronic thromboembolic pulmonary hypertension) had higher concentrations of OPN compared to patients with pulmonary embolism and that OPNs downstream target (MMP-9) are present in profibrotic areas of CTEPH tissue material." (PMID 37623509, 2023).
Classical Hodgkin Lymphoma (1 paper, 2013). "Previous studies have investigated the prognostic relevance of MMP9 in classical Hodgkin lymphoma (cHL), with negative results." (PMID 24086377, 2013).
coagulopathy (1 paper, 2009). "MMP-9 negatively correlated with SOFA, lactic acid, and coagulopathy markers (all P < 0.001) and positively with platelet count (P < 0.001)." (PMID 19799791, 2009).
cocaine abuse (1 paper, 2007). Disorders related or resulting from use of cocaine. "The results of this analysis suggest a coordinated regulation of hippocampal RECK, MMP9, protocadherins and other proteins of the cytomatrix that have not been demonstrated previously in human postmortem studies of gene expression in chronic cocaine abusers." (PMID 18000554, 2007). "We examined whether the target molecules of RECK, MMP2 and MMP9 were regulated by cocaine abuse." (PMID 18000554, 2007). "Since MMPs can degrade the entire extracellular matrix, coordinated regulation of RECK, MMP9, CTGF and EphB4 suggests expansion of the extracellular matrix occurs with morphological remodeling of the hippocampus in response to chronic cocaine abuse." (PMID 18000554, 2007).
collagenous colitis (1 paper, 2015). A type of microscopic colitis of unknown etiology. "Preliminary studies have shown associations between collagenous colitis and an MMP-9 SNP but not MMP-1 or MMP-7 SNPs." (PMID 25948887, 2015). "Interestingly, these trends were not replicated in lymphocytic colitis or collagenous colitis where MMP-9 does not seem to contribute to the severity of the disease." (PMID 25948887, 2015).
colonic disease (1 paper, 2025). "This is likely because MMP-9 fecal activity better informs activity of colonic disease, which is more useful in UC and colonic CD but misses many other CD patients." (PMID 41148805, 2025).
Congenital Muscular Dystrophy type 1D (1 paper, 2024). "In a mouse model for Congenital Muscular Dystrophy type 1D, blood-brain barrier permeability increased with an MMP-9 increase in the hippocampus." (PMID 38431757, 2024).
constrictive pericarditis (1 paper, 2023). A heart disorder in which the pericardial sac becomes thickened and fibrotic, tightening the myocardium and impeding the normal myocardial function. "Furthermore, a high level of MMP-9 was linked to poor post-operative outcomes and was an independent risk factor for post-operative complications in 22 patients with constrictive pericarditis who underwent pericardiectomy with CPB." (PMID 36671498, 2023).
Cough (1 paper, 2024). A sudden, audible expulsion of air from the lungs through a partially closed glottis, preceded by inhalation. "MMP-9 may be used as an objective serum biomarker that represents cough severity to understand the pathogenesis." (PMID 38341543, 2024). "In the present study, we investigated the signalments, comorbidities, fluoroscopic characteristics, and serum biomarkers (MMP-9, IL-6, SP-A, and SDC-1) of 51 dogs with TC with different cough grades." (PMID 38341543, 2024).
crescentic glomerulonephritis (1 paper, 2025). A histopathologic term for a pattern of diseases characterized by extensive crescent formation in the glomeruli; patients present clinically with rapid deterioration of renal function, and possible progression to end-stage renal failure within weeks or months. "MMP9 has been implicated in the orchestration of pro-inflammatory macrophage recruitment to the renal milieu during the course of experimental crescentic glomerulonephritis, signifying its critical role in the inflammatory cascade and pathogenesis of renal disorders." (PMID 40160460, 2025).
cryptococcosis (1 paper, 2025). An acute or chronic, localized or disseminated infection by Cryptococcus neoformans. "In particular, MMP-3 may be involved in CD146 shedding, and studies in patients with cryptococcosis showed high levels of MMP-9 in the cerebrospinal fluid of patients infected with C. neoformans." (PMID 40208055, 2025).
cutaneous lupus erythematosus (1 paper, 2025). An autoimmune disorder that manifests as different lupus-specific skin disorders; it can occur with systemic lupus erythematosus, or as a singular disease. "In cutaneous lupus erythematosus (CLE), lesional skin shows increased MMP-2, MMP-9, and proMMP-9 expression, with MMP-9 levels correlating with CLASI scores and improving under chloroquine therapy." (PMID 41226358, 2025).
cutis laxa (1 paper, 2016). Cutis laxa (CL) is an inherited or acquired connective tissue disorder characterized by wrinkled, redundant and sagging inelastic skin associated with skeletal and developmental anomalies and, in some cases, with severe systemic involvement. "Levels of dermal expression of MMP-3, MMP-9, and MMP-12 are increased in cutis laxa lesional fibroblasts or lymphocytes and are correlated with the degree of disruption of elastic fibers." (PMID 28116317, 2016).
Dengue hemorrhagic fever (1 paper, 2025). A serious condition caused by Dengue virus infection. "This study provided a strong support for the role of MMP-9 in causing dengue hemorrhagic fever in severe dengue viral disease." (PMID 41189711, 2025).
dentinogenesis imperfecta (1 paper, 2017). Dentinogenesis imperfecta (DGI) is a hereditary dentin defect characterized by abnormal dentin structure resulting in abnormal tooth development. "The results showed that Mmp9−/− teeth displayed a phenotype similar to dentinogenesis imperfecta, including decreased dentin mineral density, abnormal dentin architecture, widened predentin and irregular predentin-dentin boundary." (PMID 28195206, 2017).
diabetic ketoacidosis (1 paper, 2021). The metabolic condition resulted from uncontrolled diabetes mellitus, in which the shift of acid-base status of the body toward the acid side because of loss of base or retention of acids other than carbonic acid is accompanied by the accumulation of ketone bodies in body tissues and fluids. "The authors suggested that further studies are necessary to determine the role of MMP-9 in the pathogenesis of the neurologic catastrophe of brain oedema in diabetic ketoacidosis." (PMID 34827690, 2021). "MMP-9 is present on neurons in the hippocampus areas of both brain oedema and diabetic ketoacidosis patients." (PMID 34827690, 2021). "Inhibition of MMP-9 expression might help preserve neuronal function and BBB integrity during diabetic ketoacidosis." (PMID 34827690, 2021).
Dry skin (1 paper, 2017). Skin characterized by the lack of natural or normal moisture. "The mean level of MMP-9 in the serum of dry skin patients exposed to SM showed significant increase, compared with that of the normal individuals." (PMID 29531551, 2017).
duodenal ulcer (1 paper, 2021). An ulcer in the duodenal wall. "Polymorphisms of the MMPs genes (MMP-9, MMP-7, MMP-3) may contribute to a genetic risk profile for gastric and duodenal ulcers in chronic H. pylori infection." (PMID 34188075, 2021).
dystocia (1 paper, 2023). Slow or difficult obstetric labor or childbirth. "Overall, this analysis suggests that the occurrence of dystocia is largely linked to Mmp2 loss, as well as indicating that the additional loss of the other gelatinase, Mmp9, reduces this phenotype to a certain extent." (PMID 38069145, 2023). "Intriguingly, these data show that the loss of one or two alleles of Mmp9 to the Mmp2-KO background (i.e., Mmp2−/−Mmp9+/− and dKO) leads to a somewhat reversed phenotype of a decreased dystocia incidence (40-42.9%) in relation to the rate in the Mmp2−/− females (54.5%)." (PMID 38069145, 2023). "When breeding the different MMP2/MMP9-null colonies, we frequently observed pregnant females with dystocia." (PMID 38069145, 2023). "Hence, we decided to methodologically characterize the occurrence of dystocia in the following genotypes: WT, Mmp2+/−, Mmp2−/−, Mmp9+/−, Mmp9−/−, Mmp2+/−Mmp9+/−, Mmp2−/−Mmp9+/−, Mmp2+/−Mmp9−/− and Mmp2−/−Mmp9−/− (dKO)." (PMID 38069145, 2023). "Notably, in the females younger than 6 M, we found much lower rates of dystocia in general, but the pattern of higher dystocia occurrence in the Mmp2−/−, Mmp2−/−Mmp9+/− and dKO, compared to either the WT or the other Mmp9 mixed genotypes, was similar." (PMID 38069145, 2023). "Additionally, both heterozygous Mmp2+/− and Mmp9+/− showed a dystocia rate of 8.3% (2/24 and 1/12, respectively) in the >6 M-old females." (PMID 38069145, 2023). "Notably, concomitantly with the relatively low proportion of the dystocia occurrence in the Mmp9−/− females (8.3%), the histology of these uteri did not present major differences compared to the WTs in terms of the total tissue area, or the myometrium, endometrium and lumen areas." (PMID 38069145, 2023). "In contrast, no cases of dystocia were found in the WT females (0/31), and 15.6% of the Mmp9−/− pregnancies (5/32) resulted in dystocia." (PMID 38069145, 2023). "Nevertheless, the dystocia rates that were found in the Mmp9−/− (15.6%) are still considered high and non-negligible compared to the WT (0%)." (PMID 38069145, 2023).
EBV infection (1 paper, 2013). "Our finding that MMP9 was associated with EBV-infection is in line with functional studies that reported that MMP9 expression is enhanced by LMP1." (PMID 24086377, 2013). "MMP9 expression is also known to be mediated by Epstein-Barr virus infection, which is associated with cHL in about 40% of cases." (PMID 24086377, 2013). "We observed an association of MMP9 expression by neoplastic cells with EBV infection, but not with other individual variables." (PMID 24086377, 2013). "Other immunoistochemical studies investigating the association of MMP9 with EBV infection in cHL have reported negative results, and in our study MMP9 status did not correlate with Mixed Cellularity subtype (more frequently associated with EBV infection)." (PMID 24086377, 2013).
endometrial tumors (1 paper, 2023). "MMP2 and MMP9 downregulation and protein inhibition are desired effects, as their expression levels are closely related to invasion and metastasis, which also applies for endometrial tumors." (PMID 37313172, 2023).
endometritis (1 paper, 2025). An acute or chronic, usually bacterial infectious process affecting the endometrium. "Additionally, the expression levels of matrix metalloproteinases MMP2 and MMP9 were significantly upregulated (p < 0.05) in the endometritis group." (PMID 40646747, 2025). "The results demonstrate that oxidative-stress-mediated endometritis significantly upregulates MMP2, MMP9, and the TGFβ1/Smad3 pathway activity, while suppressing COL-IV expression." (PMID 40646747, 2025).
esophagitis (1 paper, 2022). An acute or chronic inflammatory disease affecting the esophageal wall. "Furthermore, MMP-9 expression is inversely correlated with protein levels of the phase II detoxification glutathione-s-transferase pi (GSTP1), with increased levels of GSTP1 in normal patients and those with esophagitis." (PMID 35267943, 2022). "Increased levels of MMP-9 are observed in tissues from patients with dysplastic BE and EAC, but not those with esophagitis or metaplastic BE." (PMID 35267943, 2022).
eumycetoma (1 paper, 2019). "Geneugelijk and colleagues demonstrated the presence of both MMP-2 and MMP-9 in eumycetoma lesions caused by M. mycetomatis." (PMID 31295246, 2019).
Fabry disease (1 paper, 2024). Fabry disease (FD) is a progressive, inherited, multisystemic lysosomal storage disease characterized by specific neurological, cutaneous, renal, cardiovascular, cochleo-vestibular and cerebrovascular manifestations. "Recently, we showed altered MMP9 and angiostatin levels in the serum of patients with Fabry’s disease compared with healthy controls, suggesting a higher extracellular matrix turnover in Fabry's disease." (PMID 38374995, 2024).
gliosarcoma (1 paper, 2017). A rare histological variant of glioblastoma (WHO grade IV) characterized by a biphasic tissue pattern with alternating areas displaying glial and mesenchymal differentiation (WHO). "Further, MMP-2 and MMP-9 were shown to be distinctly expressed in mesenchymal tumor areas of gliosarcomas." (PMID 28234925, 2017).
gonococcal infection (1 paper, 2019). "MMP9 promotes Hepatitis B virus replication, and is of significant importance in response to gonococcal infection." (PMID 31137698, 2019).
gram-positive bacterial infections (1 paper, 2010). Infections caused by bacteria that retain the crystal violet stain (positive) when treated by the gram-staining method. "Understanding the regulatory mechanisms underlying LTA-induced MMP-9 expression and functional changes in astrocytes may provide a new therapeutic strategy for Gram-positive bacterial infections in brain disorders." (PMID 21092323, 2010).
Headache (1 paper, 2016). Cephalgia, or pain sensed in various parts of the head, not confined to the area of distribution of any nerve. "Women migraineurs have increased plasma MMP-9 concentrations during headache vs. interictal phases, and a particular MMP-9 haplotype." (PMID 27148260, 2016).
Heat Stroke (1 paper, 2017). A condition caused by the failure of body to dissipate heat in an excessively hot environment or during PHYSICAL EXERTION in a hot environment. "When those four validated reference genes, SDHA, POLR2A, IPO8 and HMBS, were used for normalization, increased cerebral expressions of AQP4, CLDN5, OCLN, ZO1 and MMP9 were detected in heat stroke group." (PMID 28490769, 2017). "Heat stroke cases showed an increase in brain water content, which was found to be positively correlated with MMP9, OCLN, ZO1 and CLDN5 mRNA." (PMID 28490769, 2017). "The present study, for the first time, reports increased cerebral MMP9, CLDN5, OCLN, ZO1 and AQP4 in heat stroke and suggest a crucial role of reference gene selection when using postmortem human tissues." (PMID 28490769, 2017). "Relative mRNA quantification using Taqman real-time PCR assay demonstrated increased calibrated normalized relative quantity (CNRQ) values of MMP9, CLDN5, OCLN, ZO1 and AQP4 in heat stroke cases." (PMID 28490769, 2017).
helminth infections (1 paper, 2021). "Furthermore, in helminth infections (neurocysticercosis) differential expression of circulating MMP-9 enables discrimination of asymptomatic and symptomatic patients." (PMID 33891967, 2021).
hemarthrosis (1 paper, 2025). Bleeding into the joints. "Pertaining to M2 markers, six of eight M2 markers were affected (up-/down-regulated with hemarthrosis and/or affected by FVIII-treatments) on day 3 and 14 (Arg1, Chil3, Mmp9, Fcgr4, Pparg, Irf4)." (PMID 40388523, 2025).